RNU6-544P (RNA, U6 small nuclear 544, pseudogene)
Gene: Small nuclear RNA gene on chromosome 11 (80,527,960 to 80,528,066, forward strand). Ensembl gene ENSG00000200146.
Homologues: Orthologues: chimpanzee U6 (99% identical), macaque U6 (91% identical), rat LOC120099618 (83% identical), rabbit U6 (78% identical), dog U6 (76% identical), mouse Gm55126 (72% identical), guinea pig U6 (68% identical). Paralogues in human: RNU6-727P (86% identical), RNU6-166P (85% identical), RNU6-41P (85% identical), RNU6-1060P (84% identical), RNU6-1303P (84% identical), RNU6-15P (84% identical), RNU6-30P (84% identical), RNU6-44P (84% identical), RNU6-485P (84% identical), RNU6-748P (84% identical), RNU6-949P (84% identical), RNU6-1011P (83% identical), and 1283 more.